ACE (angiotensin I converting enzyme)
Diseases named in the same sentence as ACE in open-access papers (continued):
Sharing a sentence is not in itself a finding about the gene and the disease.
Hypertension (continued). "The clinical trials revealed that Renin angiotensin system (RAS) and angiotensin converting enzyme (ACE) are important targets to control or manage the hypertension." (PMID 27047315, 2015). "It has been reported that ACE inhibitors have beneficial effects on hypertension and statins on hyperlipidemia." (PMID 25973747, 2015). "In fact, ACE inhibitors (ACEi) or Ang II receptor antagonists are widely used for the treatment of the hypertension as they are known to have antifibrotic effects on the kidney." (PMID 25945342, 2015). "Both 7-locus and 8-locus models suggest that the listed SNPs in AGT, ACE, and AT1R genes were important in association with hypertension." (PMID 25961019, 2015). "Plasma levels of T-cad correlated negatively with BMI, the presence of hypertension and the use of an ACE inhibitor or ARB in both males and females." (PMID 26083608, 2015). "Our results suggest that AGT, ACE, and AT1R genes have an overall hypertension susceptibility effect." (PMID 25961019, 2015). "In our study, 30 % overall, 11.1 % of people with diabetes and hypertension, 9.2 % of people with albuminuria and hypertension received ACE inhibitor therapy." (PMID 26535132, 2015). "Patients with prior MI and hypertension should be treated with beta-blockers and angiotensin-converting enzyme (ACE) inhibitors." (PMID 26718096, 2015). "The development of hypertension in this model is mainly due to a high production of Ang II, which is generated through the activation of ACE by converting the inactive decapeptide Ang I to the potent vasoconstriction octapeptide Ang II." (PMID 26184305, 2015). "For hypertension association, AGT gene haplotype (T174M, M235T, G-6A, A-20C, G-152A, and G-217A) had been reported to interact with I/D of the ACE gene." (PMID 25961019, 2015). "Substances displaying inhibitory activity against dipeptidyl carboxypeptidase (angiotensin-converting enzyme or ACE, EC 3.4.15.1) play an important role in controlling the development of hypertension by regulating the renin–angiotensin system." (PMID 25408464, 2015). "The unbalanced function based MDR model can explore the epistasis network of SNPs AGT, ACE, and AT1R of RAS genes and identify strongly significant hypertension association." (PMID 25961019, 2015). "Conventional pharmacological treatment for hypertension includes diuretics, angiotensin converting enzyme (ACE) inhibitors, angiotensin receptor blocker, β-receptors blockers, L-Type calcium channel blockers, and central α-receptors agonists." (PMID 26180582, 2015). "Some stroke subjects (57 %) were diagnosed with hypertension before the event, and most of them were being treated with angiotensin-converting enzyme (ACE) inhibitors." (PMID 26420632, 2015). "Hypertension in these patients should be treated with beta-blockers plus an ACE inhibitor or ARB with addition of a thiazide or thiazide-like diuretic if needed." (PMID 26718096, 2015). "The I allele of ACE gene and +1166 C allele of AT1R gene are reportedly associated with hypertension." (PMID 25961019, 2015). "ACE inhibitors have a valuable role to play in patients who have hypertension and erectile dysfunction." (PMID 26557995, 2015). "The agents used to treat hypertension in clinic include diuretics, calcium channel blockers, beta adrenergic antagonists, angiotensin-converting enzyme (ACE) inhibitors, and angiotensin II type I receptor antagonists." (PMID 26798397, 2015). "Animals with hypertension after renal injury and treated with ACE inhibitors (ACEi) showed decreased cardiac ACE and ACE2 activity and an improvement of cardiac structure." (PMID 26010093, 2015). "The use of ACE inhibitors has proven to be an effective strategy in the prevention and treatment of hypertension-related diseases, mainly by bringing about a significant alleviation of hypertension, as well as by affording end-organ protection." (PMID 26039337, 2015).
Hypertension (continued). "In March 2010 a 24 year old Caucasian man with marphanoid habitus (height: 175 cm; weight: 65 Kg) was referred to us for severe hypertension that was resistant to beta blockers, angiotensin converting enzyme (ACE) inhibitors, and diuretics." (PMID 26084817, 2015). "The ACE D/D genotype has also been linked with impaired circadian blood pressure variation in T2DM, which is associated with autonomic neuropathy, hypertension, and limited kidney function." (PMID 26074879, 2015). "Among these, food protein-derived angiotensin-converting enzyme (ACE) inhibitory peptides have received much attention for prevention of hypertension as well as for therapeutic purposes." (PMID 26184305, 2015). "The most commonly identified PPO using the ACOVE criteria were calcium and vitamin D supplements in patients with osteoporosis (13.3%) and ACE inhibitors or angiotensin-receptor blockers in patients with hypertension and comorbid vascular diseases (10.8%)." (PMID 25887546, 2015). "On the other hand, we found that the high salt diet worsened the hypertension, accelerated the renal damage and increased kidney ACE/ACE2 protein ratio, as previously reported." (PMID 26495970, 2015). "The results show that ACE and PAI-1 genes are significantly associated with the hypertension and hypercholesterolemia, and clearly illustrate a spectrum of five polymorphisms highly detected in the two groups: ACE, PAI-1, MTHFR, FXIII and β-fibrinogen." (PMID 25973747, 2015). "Captopril was the first effective antihypertensive drug designed to bind and inhibit the active sites of ACE, and represented a breakthrough in the treatment of hypertension." (PMID 26661890, 2015). "There are a number of antihypertensive drugs such as beta-blockers, angiotensin-converting enzyme (ACE) inhibitors, angiotensin receptor blockers (ARBs), calcium channel blockers, and diuretics being used to treat high blood pressure." (PMID 26686682, 2015). "In subjects with essential hypertension zofenopril has been shown to be as effective as beta-blockers, diuretics, calcium channel blockers, other ACE-inhibitors, and Angiotensin Receptor Blockers (ARBs)." (PMID 26347187, 2015). "About 8% of the adult population is taking angiotensin-converting enzyme (ACE) inhibitors to treat cardiovascular disease including hypertension, myocardial infarction and heart failure." (PMID 24691203, 2014). "is an angiotensin-converting enzyme (ACE) inhibitor used in the treatment of heart failure and hypertension." (PMID 25481012, 2014). "This patient had pregnancy-related hypertension: ACE D/D homozygosity can potentially contribute to the pathogenesis of essential hypertension, as well hypertension at a young age and low body weight at birth." (PMID 25587456, 2014). "As hypertension occurs when the angiotensin converting enzyme (ACE, EC 3.4.15.1) catalyzes the conversion of angiotensin I into angiotensin II." (PMID 25364320, 2014). "36.4% of drugs purchased were indicated to treat heart failure, hypertension or arrhythmia (beta or calcium blockers, ACE inhibitors or ARB, furosemide, doxazosin and anti-arrhythmics)." (PMID 25342142, 2014). "At present, the therapeutic protocols of arterial hypertension include a number of synthetic inhibitors of ACE, such as captopril, lisinopril, or enalapril." (PMID 25050143, 2014). "When considering the combination of death and rehospitalization during follow-up period, there was significant increase of age, hypertension, diabetes mellitus, use of ACE inhibitors (ACEi), sCr, and BUN values in patients who develop events." (PMID 25101304, 2014). "The main aim of the current study is thus to assess the prevalence of left ventricular hypertrophy in Ethiopian hypertensive patients and role of ACE inhibitors in preventing LVH in patients with hypertension." (PMID 24444396, 2014).
Hypertension (continued). "Twenty-nine (8 females) out of 44 patients (66%) suffered from controlled arterial hypertension and were taking diuretics (38%), Ca-antagonists (34%), beta-blockers (34%), and ACE-inhibitors (28%)." (PMID 24885001, 2014). "Experimental evidence suggests that antihypertensive or angiotensin I-converting enzyme (ACE) inhibitor treatment can offer a clinical advantage in hypertension." (PMID 24616741, 2014). "The Infinity ACE is widely used for monitoring the effects of ACE inhibitors in the treatment of hypertension and heart failure." (PMID 25050143, 2014). "The inhibition of ACE is considered a useful therapeutic approach in the development of drugs to control hypertension." (PMID 24672576, 2014). "In the context of hypertension, numerous ACE-inhibitory, and antioxidant peptides have been identified from different egg protein hydrolysates." (PMID 25502445, 2014). "In our analysis, hypertension, ACE-inhibitors, All antagonists, beta blockers, and calcium antagonists were found to confound this relationship." (PMID 24422708, 2014). "In this case-control study, we examined possible associations between polymorphisms of the AGT, ACE, and AGTR1 genes and hypertension in the south Indian population age between 30 and 70 years." (PMID 24860821, 2014). "In the process of hypertension, ACE plays an important role in regulating blood pressure, and ACE inhibitors are considered to be one of the therapeutic methods for treating anti-hypertension." (PMID 25185066, 2014). "Group III included patients with MS and concomitant arterial hypertension, who were treated with ACE inhibitors for at least three months." (PMID 25050143, 2014). "In multivariate logistic regression analysis, ACE D/D genotype (p = 0.035), diabetes-mellitus (p = 0.019) and hypertension (p = 0.001) were found to be independent predictive factors for RVO." (PMID 25161389, 2014). "In particular, soluble ACE concentration was lower before pacemaker implantation than in the healthy individuals and in patients with hypertension with preserved ejection fraction and it increased in parallel with the improvement of cardiac function." (PMID 24691269, 2014). "L-NAME hypertension significantly (P<0.05) enhanced the activity of ACE in heart and aorta compared with control and this increase was attenuated by SA treatment." (PMID 25531679, 2014). "ACE expression on SMCs is largely responsible for hypertension via vasoconstriction mediated by excessive production of Ang II." (PMID 25222748, 2014). "More than 10% of hypertensive patients have raised aldosterone levels, and drugs that block the mineralocorticoid receptor (MR), the main target receptor of aldosterone, are used to treat hypertension that is resistant to ACE inhibition and AT1R antagonism." (PMID 25136585, 2014). "ACE inhibitors are the fifth most described drugs and represent a cornerstone in the treatment in cardiovascular diseases (hypertension, heart failure)." (PMID 24690767, 2014). "Lisinopril is a drug of the angiotensin-converting enzyme (ACE) inhibitor class that is primarily used in the treatment of hypertension, congestive heart failure, and heart attacks." (PMID 24959410, 2014). "Lisinopril is an angiotensin-converting enzyme (ACE) inhibitor, primarily used for the treatment of hypertension, congestive heart failure, and heart attack." (PMID 24959410, 2014). "Several ACE inhibitors, including captopril, lisinopril, and enalapril, are synthetic molecules which are clinically used as anti-hypertension agents." (PMID 25185066, 2014). "For evaluation of genotype effect on the risk of hypertension, four SNPs were chosen: two SNPs (AGT and ACE) related to renin-angiotensin-aldosterone system and other two SNPs (ADM and CACNB2) newly identified in genome-wide association studies." (PMID 25313554, 2014).
Hypertension (continued). "While there are no available pediatric studies to support their superiority over other drug classes, ACE inhibitors seem to be the most frequently prescribed agents for children with hypertension." (PMID 24522942, 2014). "Captopril is an effective orally administered ACE inhibitory drug widely used in treating hypertension." (PMID 25222748, 2014). "The current ACE inhibitors widely used in the treatment of hypertension, congestive heart failure and diabetic nephropathy 9 are designed based on the principle that suppression of angiotensin II formation and bradykinin degradation is clinically important." (PMID 24289879, 2014). "Thirty three of 113 (29.2%) patients who had hypertension with concurrent PAD were on an ACE inhibitor or ARB." (PMID 24913468, 2014). "Angiotensin I-converting enzyme (ACE) (EC 3.4.15.1) is a hypertension-responsible glycoprotein present both in biological fluids and many tissues." (PMID 25123137, 2014). "In humans, treatment of hypertension with a mineralocorticoid receptor antagonist additionally to an angiotensin I-converting enzyme blocker or an AT1R-blocker, also resulted in reduction of albuminuria/proteinuria." (PMID 25551569, 2014). "Its involvement in the modulation of physiological actions of peptide hormones has positioned ACE as an important therapeutic target for the treatment of hypertension and cardiovascular disorders." (PMID 24289879, 2014). "Here we report a single center, prospective clinical study to establish a relationship between circulating ACE, sACE2 and clinical parameters, such as hypertension or cardiac performance." (PMID 24691269, 2014). "Inhibition of ACE enzymatic activity by selective ACE inhibitors blocks the generation of Ang II and thereby acts as a suitable approach for the treatment of high blood pressure." (PMID 24475296, 2014). "Remarkably, SA attenuated high blood pressure, myocardial, vascular dysfunction, cardiac fibrosis, oxidative stress and ACE activity." (PMID 25531679, 2014). "These vasopressor activities can be blocked either by ACE-inhibitors, a standard treatment for hypertension or by Ang II receptor antagonists that inhibit Ang II-mediated vasopressor effects." (PMID 25309424, 2014). "At present, the renin-angiotensin system has become a key target for drugs combating hypertension and, more specifically, various synthetic ACE inhibitors are widely used to treat cardiovascular disorders." (PMID 24619242, 2014). "A case-control association study was conducted to investigate a possible involvement of polymorphisms of three RAS genes: AGT M235T (rs699), ACE I/D (rs4340) and G2350A (rs4343), and AGTR1 A1166C (rs5186) in essential hypertensive patients." (PMID 24860821, 2014). "This is the first report to evaluate the simultaneous association of ACE, AGTR1, and AGT gene polymorphisms in essential hypertension by haplotype based analyses and gender specific association in south India." (PMID 24860821, 2014). "Our fine-mapping results for ACE activity and for young-onset hypertension were confirmed by additional sets of independent samples." (PMID 23469169, 2013). "According to the NICE guidelines, calcium channel blockers are preferred over ACE-inhibitors for monotherapy of uncomplicated hypertension in black adults of any age and in white adults over the age of 55 years." (PMID 24067062, 2013). "Of all antihypertensive active substances, beta blockers were the most frequently prescribed substance class (63.7%, N = 671), ACE-inhibitors were taken by 52.4% (N = 586) of the treated hypertension patients." (PMID 23782640, 2013). "The objective of the present study was to systemically examine the association between polymorphisms in the RAAS candidate genes (REN, AGT, ACE, AGTR, and CYP11B2) and hypertension." (PMID 24015270, 2013). "The Canadian Hypertension Education Program has recommended against use of ARBs and ACE inhibitors together except in patients with HF refractory to ACE inhibitor." (PMID 23866091, 2013).
Hypertension (continued). "The majority of subjects had hypertension (81%) and only a few had heart failure (6%); 3,255 subjects (67%) had been treated with an ACE inhibitor." (PMID 23948883, 2013). "The essential oil inhibited ACE activity in vitro in a concentration-dependent manner and therefore could have the ability to moderate the conversion of angiotensin-I to angiotensin-II which is a vasoconstrictor that has been implicated in the development of hypertension." (PMID 24348547, 2013). "ACE inhibitors(inhibitors of angiotensin-converting enzyme)are used primarily in treatment of hypertension and heart failure." (PMID 24265719, 2013). "One frequently cited challenge of treating hypertension among black adults is the lesser blood pressure response to certain medications such as ACE-inhibitors (ACEI)." (PMID 24067062, 2013). "Therapy for hypertension in HF patients includes beta-blockers, ACE inhibitors, ARBs, diuretics, hydralazine, and isosorbide dinitrate." (PMID 23476746, 2013). "Of the studied individuals, 36 had hypertension, and 31 received ACE inhibitors or AT1 receptor antagonists." (PMID 23326585, 2013). "According to the chi-square test P values (P<0.05) and odds ratios, rs3789678 and rs2493132 within AGT, rs4305 within ACE, rs275645 within AGTR1, rs3802230 and rs10086846 within CYP11B2 were shown to associate with hypertension." (PMID 24015270, 2013). "According to Chi-square test and logistic regression analysis, rs3789678 within AGT, rs4305 within ACE, rs275645 within AGTR1, rs3802230 within CYP11B2 were shown to associate with hypertension." (PMID 24015270, 2013). "Currently, the application of ACE peptide inhibitors has become an important way to cure hypertension, congestive heart failure (CHF), and chronic renal disease, but its side effects to the health are also noticeable." (PMID 25969772, 2013). "ACE inhibitors such as captopril and lisinopril play key roles in treating hypertension and maintaining the electrolyte balance." (PMID 24359711, 2013). "Angiotensin converting enzyme inhibitors (ACE-i) are used to treat arterial hypertension and heart failure." (PMID 23841100, 2013). "Of 41 SNPs genotyped, rs3789678 and rs2493132 within AGT, rs4305 within ACE, rs275645 within AGTR1, rs3802230 and rs10086846 within CYP11B2 were shown to associate with hypertension." (PMID 24015270, 2013). "Compound 3d exhibited strongest in vitro inhibition of ACE activity suggesting its potential in treating hypertension." (PMID 23666006, 2013). "We then analyzed the effect of hypertension, ACE inhibitors, and AT1 receptor antagonists on the expression levels of those genes which showed to be the most suitable reference genes." (PMID 23326585, 2013). "In patients with hypertension the inhibition of ACE-1 by captopril is a common treatment to lower the blood pressure by decreasing the generation of ANG-1-8." (PMID 23724017, 2013). "ACE cleaves angiotensin I to produce angiotensin II, a powerful vasoconstrictor that has been identified as a major factor in renal and hypertension." (PMID 23847460, 2013). "Angiotensin I-converting enzyme (ACE) inhibitors have been reported to reduce mortality in patients with hypertension." (PMID 24215325, 2013). "Captopril has been established in clinical practice since many years as angiotensin-I-converting enzyme (ACE) inhibitor to treat cardiovascular diseases such as congestive heart failure and arterial hypertension." (PMID 24223058, 2013). "Angiotensin converting enzyme (ACE) inhibitors are effective hypertension medications and are commonly used in the elderly." (PMID 23948883, 2013). "It is remarkable that ACE inhibitors which are in use for congestive heart failure and arterial hypertension for decades also reveal anticancer activity." (PMID 24223058, 2013). "Over the last reports, the first ACE peptide inhibitor was discovered from snake venom due to its significant effects on the hypertension." (PMID 25969772, 2013).